CYP3A4 (cytochrome P450 family 3 subfamily A member 4)
Diseases named in the same sentence as CYP3A4 in open-access papers (continued):
Sharing a sentence is not in itself a finding about the gene and the disease.
lung adenocarcinoma (1 paper, 2023). A carcinoma that arises from the lung and is characterized by the presence of malignant glandular epithelial cells. "In lung adenocarcinoma samples from patients, CYP3A4 mRNA and protein expression has been demonstrated to significantly exceed the expression in normal lung tissues." (PMID 37686184, 2023). "In the present study, the copy number alterations of two drug-metabolizing CYP genes, CYP2C8 and CYP3A4, were determined in lung adenocarcinoma samples using normal lung tissues or blood samples for normalization." (PMID 37686184, 2023). "A sensitive qPCR-based method with an optimal normalization procedure was presented here for the assessment of the copy numbers of paclitaxel-metabolizing CYP2C8 and CYP3A4 in lung adenocarcinoma samples." (PMID 37686184, 2023). "Alterations in copy numbers of paclitaxel-metabolizing CYPs (CYP2C8, CYP3A4) were aimed to be determined in primary lung adenocarcinoma samples prior to therapy." (PMID 37686184, 2023). "For the estimation of patients’ paclitaxel-metabolizing capacity, CYP2C8, CYP3A4 and CYP3A5 alleles (CYP2C8*3, CYP2C8*4, CYP3A4*1B, CYP3A4*22, CYP3A5*3) most common in Caucasian populations were identified in lung adenocarcinoma patients on paclitaxel therapy (N = 17)." (PMID 37686184, 2023). "In the treatment naïve lung adenocarcinoma samples, the multiplication of paclitaxel-metabolizing CYP2C8 and/or CYP3A4 was detected, and the CYP copy number increase was more prevalent in non-responder patients than in responders to paclitaxel therapy." (PMID 37686184, 2023). "The copy numbers of both the target (CYP2C8, CYP3A4) and the reference genes (ALB, B2M, BCKDHA, F5, CD36, MPO, TBP, RPPH1) established in primary lung adenocarcinoma by the qPCR-based method were congruent with those determined by next-generation sequencing (for 10 genes, slope = 0.9498, r2 = 0.72)." (PMID 37686184, 2023). "For the paclitaxel-metabolizing CYPs, deletion of CYP2C8, but not of CYP3A4 was detected in primary lung tumour and in lung and liver metastases (the average copy number of CYP2C8 in primary lung adenocarcinoma: 1.60, in lung metastasis: 1.47, in liver metastasis: 1.08)." (PMID 37686184, 2023).
mantle cell lymphoma (1 paper, 2008). Mantle cell lymphoma is a rare form of malignant non-Hodgkin lymphoma affecting B lymphocytes in the lymph nodes in a region called the ``mantle zone''. "Nevertheless, CYP3A4 inhibitors should not be given concomitantly with higher temsirolimus doses, such as those being investigated in clinical trials (e.g., 175 mg for mantle cell lymphoma)." (PMID 18458675, 2008).
multiple sclerosis (1 paper, 2022). A progressive autoimmune disorder affecting the central nervous system resulting in demyelination. "The prescription information of Sativex, a cannabis extract preparation approved for symptomatic treatment of multiple sclerosis patients, warns that CYP3A4, 1A2, 2B6, 2C9, and 2C19 are inhibited, and the mRNA expression of CYP1A2, 2B6, and CYP3A4 is induced." (PMID 35329893, 2022).
Mycoplasma infection (1 paper, 2017). "Elimination of Mycoplasma infection restored the levels of ALB, TF, and CYP3A4 genes as well as proteins to normal levels." (PMID 29075618, 2017).
myeloid neoplasm (1 paper, 2026). Proliferation of myeloid cells originating from a primitive stem cell. "Venetoclax (VEN), a selective BCL-2 inhibitor predominantly metabolized by CYP3A4, is a cornerstone therapeutic for myeloid neoplasms (MNs)." (PMID 41915767, 2026).
neuroblastoma (1 paper, 2009). Neuroblastoma (NB) is the most common solid, extracranial childhood tumor. "VPA also induced the expression of CYP3A4 in this neuroblastoma cell line." (PMID 21217856, 2009). "In the case of the effects of VPA and TSA on expression of CYP3A4 protein in neuroblastoma cells, both these drugs essentially did not influence its expression in S-type UKF-NB-4 and SK-N-AS cell lines." (PMID 21217856, 2009).
Neurodevelopmental delay (1 paper, 2025). "Polymorphisms in CYP3A4, CYP2C19, and CYP1A2 could impair detoxification of environmental toxicants, while dysfunction in CYP2E1 and CYP2D6 has been linked to oxidative stress and mitochondrial impairment—both implicated in neurodevelopmental delays." (PMID 40386062, 2025).
non-Hodgkin lymphoma (1 paper, 2019). Distinct from Hodgkin lymphoma both morphologically and biologically, non-Hodgkin lymphoma (NHL) is characterized by the absence of Reed-Sternberg cells, can occur at any age, and usually presents as a localized or generalized lymphadenopathy associated with fever and weight loss. "Considering that high antiemetic rates can be expected without using aprepitant and that vincristine interact with CYP3A4, aprepitant might not be needed in patients with non-Hodgkin lymphoma receiving CHOP or R-CHOP regimen." (PMID 31832222, 2019).
nonalcoholic fatty liver (1 paper, 2023). "Hepatic mRNA VDR levels and the expression of genes downstream the VDR-D pathway [cytochrome P450 (CYP) 2R1, CYP27A1, and CYP3A4] were also increased in patients with nonalcoholic fatty liver (NAFL) compared to healthy individuals." (PMID 37175993, 2023).
orthostatic hypotension (1 paper, 2025). Sudden fall of the blood pressure of at least 20/10 mm Hg when a person stands up. "Despite significantly higher Css min plasma concentrations in CYP3A4*22 allele carriers (which theoretically could increase dose-dependent effects), no reliable association was found between this marker and systemic ADRs such as orthostatic hypotension or dizziness." (PMID 40863448, 2025).
ovarian failure (1 paper, 2021). "Patients with the CYP3A4*1B variant who were aged <45 years when receiving treatment showed a significantly longer time to ovarian failure than patients homozygote for CYP3A4*1A." (PMID 34572825, 2021).
parasite infection (1 paper, 2024). "However, K98 also induced the de-differentiation of the HLCs and a decrease in the expression of the mature hepatocyte markers CYP3A4, Albumin and NTCP, and we hypothesize that this is the reason that we observe reduced parasite infection in K98-treated cells." (PMID 38770342, 2024).
pneumonia (1 paper, 2014). An acute, acute and chronic, or chronic inflammation focally or diffusely affecting the lung parenchyma, caused by an infection in one or both of the lungs (by bacteria, viruses, fungi, or mycoplasma.). "A 1.1-year-old boy, suffering from pneumonia, received the CYP3A4 inhibitor erythromycin and the CYP3A4 substrate fentanyl." (PMID 24696691, 2014).
Priapism (1 paper, 2023). A painful and harmful medical condition in which the erect penis doesn't return to its flaccid state, despite the absence of both physical and psychological stimulation, within four hours. "Co-administration of tamsulosin and other potent CYP3A4 inhibitors could increase plasma concentration of tamsulosin and lead to severe hypotension or priapism." (PMID 37972000, 2023).
Pure red cell aplasia (1 paper, 2026). A type of anemia resulting from suppression of erythropoiesis with little or no abnormality of leukocyte or platelet production. "This study reports a rare case of a sustained DDI between Apa and cyclosporine (CsA)-a CYP3A4 substrate-in a patient with metastatic hormone-sensitive prostate cancer (mHSPC) and primary pure red cell aplasia (PRCA)." (PMID 41743913, 2026).
sarcopenia (1 paper, 2012). Progressive decline in muscle mass due to aging which results in decreased functional capacity of muscles. "However, the impact of sarcopenia on CYP3A4 activity deserves further investigations, including phenotypic and genotypic testing." (PMID 22666367, 2012).
sexual dysfunction (1 paper, 2024). Disturbances in sexual desire and the psychophysiologic changes that characterize the sexual response cycle and cause marked distress and interpersonal difficulty. "Additionally, this process can be complicated by genetic variations (e.g., CYP2C19 and CYP3A4) alternating the metabolism of SSRIs and comorbid psychiatric disorders contributing to sexual dysfunction." (PMID 38263040, 2024).
skin infection (1 paper, 2024). An inflammatory process affecting the skin, caused by bacteria, viruses, parasites, or fungi. "Specifically, ketoconazole is an antifungal drug that can treat skin infections caused by a fungus and is one of the well-known CYP3A4 inhibitors." (PMID 38472201, 2024).
skin reaction (1 paper, 2012). "This could be partly explained by recent reports which showed that NVP was metabolically activated to quinone methidine, a toxic reactive metabolite, by CYP3A4, and, to a lesser extent, CYP2D6, CYP2C19, and CYP2A6, and that this reactive metabolite was responsible for NVP-induced skin reactions." (PMID 22957276, 2012).
viral hepatitis (1 paper, 2021). An acute or chronic inflammation of the liver parenchyma caused by viruses. "After longer exposure, IFN-α can enhance CYP3A4 at the functional level, consistent with data from patients with viral hepatitis chronically treated with IFN-α." (PMID 34071580, 2021).
visceral leishmaniasis (1 paper, 2024). A severe form of leishmaniasis characterized by irregular bouts of fever, substantial weight loss, swelling of the spleen and liver, and anemia (which may be serious). "It was reported that the phenotypic activities of CYP3A4 and CYP2C19 were significantly reduced in Brazilian patients during the acute phase of visceral leishmaniasis." (PMID 38240984, 2024).
vitamin D metabolism disorders (1 paper, 2024). "CYP3A4 also participates in vitamin D metabolism and promotes vitamin D metabolism disorders, including increased elimination." (PMID 39125420, 2024).
Wilson disease (1 paper, 2021). A very rare inherited multisystemic disease presenting non-specific neurological, hepatic, psychiatric or osseo-muscular manifestations due to excessive copper deposition in the body. "Gene expression of analyzed enzymes ranged between 18 and 65% compared to control group and significantly lower protein content of CYP1A1, CYP1A2, CYP2C8, CYP2C9, CYP3A4 and CYP3A5 enzymes was observed in Wilson’s disease." (PMID 34117631, 2021).
cancer (205 papers, 1998 to 2026). A tumor composed of atypical neoplastic, often pleomorphic cells that invade other tissues. "We assayed 1,214 variants across six CYP3A4 regulatory regions, integrating variants from global populations, cancer genomes, and archaic humans." (PMID 42079203, 2026). "Bioinformatic analysis also confirms that one of the top acetaminophen targets interacting with cancer-related genes is the sequences that encode members of the cytochrome P450 superfamily of enzymes (CYP3A4, CYP1A1, CYP1A2)." (PMID 41516250, 2025). "The rs2242480 polymorphism within the CYP3A4 gene had shown an association with certain cancers, such as those affecting the prostate, breast, and ovaries." (PMID 41242742, 2025). "CDK9 and CYP3A4 are critical components of the complex network underlying cancer biology, and their inhibition represents promising targets for therapeutic intervention." (PMID 39498375, 2024). "Expression of CYP3A4 varies between individuals and has been associated with outcome in adult cancers." (PMID 32848787, 2020). "The association of reduced CYP3A4 expression in the presence of cancer is associated with the inflammatory response and the release of cytokines such as IL-6 from the cancer into the blood." (PMID 33076284, 2020). "A meta-analysis comprising 55 separate studies including 22,072 cancer cases and 25,433 controls found a significant association between CYP3A4*1B and cancer risk especially leukemia in the overall population." (PMID 33192522, 2020). "Although there are many studies on CYP3A4 gene polymorphism and cancer susceptibility, the underlying mechanism is still unclear and needs to be further investigated." (PMID 33192522, 2020). "The concomitant administration of DOACs with anti-cancer and adjunctive pharmacotherapies that are inhibitors or inducers of Pg-P and CYP3A4 poses a theoretical risk of VTE or bleeding by pushing circulating DOAC levels outside the therapeutic range." (PMID 31297188, 2019). "In cancer patients with concomitant drugs that inhibit CYP3A4, e.g., fluconazole, there is a risk of drug-drug interactions with increased concentrations of lipid-soluble statins and subsequently increased risk of adverse events and myotoxicity." (PMID 30342545, 2018). "Multivariate linear regression analysis showed that the presence of cancer, CYP3A4*1G polymorphism, and miR-142 were independent factors influencing the variability of CYP3A4 mRNA expression with the model R2 = 0.29." (PMID 27211076, 2016). "CYP2R1, CYP27A1 and CYP3A4 are 3 major 25-hydroxylases responsible for the initial hydroxylation to convert vitamin D to 25 (OH)D, and their genetic polymorphisms have been found associated with different risks for developing certain types of cancer." (PMID 40630116, 2025). "Single-nucleotide polymorphisms in the CYP3A4 promoter region (A290G) (i.e., CYP3A4*1B) have been implicated as a possible cause of this variability; hence, it may be considered a risk factor for cancer." (PMID 37047003, 2023). "Indeed, the administration of P-glycoprotein transporter inhibitors or CYP3A4 inhibitors, such as ketoconazole in cancer treatment, can enhance the exposure to DOACs, predisposing patients to a higher incidence of hemorrhagic events." (PMID 36233581, 2022). "CYP3A4*1B is one of the most studied polymorphisms of CYP3A4 in cancer patients." (PMID 36358854, 2022). "CYP2J2 and CYP3A4 play a key role in the metabolism of cancer drugs known to cause cardiotoxicity." (PMID 33659048, 2021). "Alterations of P-glycoprotein (P-gp) and cytochrome P450 3A4 (CYP3A4) contribute to multidrug resistance and intestinal metabolism in a variety of cancer types, which may be implicated in DM development." (PMID 33053111, 2020). "This review examines the age-dependent regulation of hepatic GGA levels via MAOB and CYP3A4 pathways and assesses its relevance to age-related cancer biology." (PMID 41142201, 2025).
cancer (continued). "Beyond their potential roles in liver tumor biology, both MAOB and CYP3A4 are well-characterized enzymes with established physiological functions in non-cancer contexts." (PMID 41142201, 2025). "The subsequent increase in CYP3A4 levels facilitates irinotecan detoxification, thus promoting acquired resistance in cancer cells." (PMID 39931465, 2025). "Crosstalk with hypoxia-inducible factors (e.g., HIF-2α) has also been shown to amplify PXR-mediated transcription of drug resistance genes such as CYP3A4, which further complicates therapeutic outcomes in cancer." (PMID 40869940, 2025). "On the other hand, abnormal DNA methylation patterns are commonly observed in cancer and can significantly impact the expression of drug-metabolizing enzymes like CYP3A4." (PMID 39931465, 2025). "Since many cancer patients undergo combination therapies, and CYP3A4 is vital in drug metabolism, its inhibition or induction by one drug can alter the plasma levels of others, potentially leading to treatment failure or increased toxicity." (PMID 39498375, 2024). "CYP3A4, involved in cancer cell metabolism and chemotherapy efficacy, has been identified as a potential target for enhancing treatment effectiveness through its inhibition." (PMID 39204124, 2024). "CYP3A4 and CYP3A5 catalyze the formation of hydroxy- and dihydroxy-derivatives of paclitaxel and docetaxel, thereby causing their inactivation in cancer cells." (PMID 39682707, 2024). "Tumors with high CYP3A4 expression can metabolize mitotane more effectively, protecting cancer cells from its cytotoxic effects." (PMID 39682247, 2024). "Several cancer and adjunctive therapies (including anti-emetics, opioids, and antibiotics) can alter CYP3A4 metabolism and, therefore, careful consideration is encouraged before administering these therapies together with DOACs." (PMID 38891849, 2024). "This trial was the first DDI study with bosentan used as a moderate CYP3A4 inducer in cancer patients." (PMID 38399397, 2024). "Topological analysis of the PPI network, using the STRING database and Cytoscape 3.10.2, identified seven core targets crucial in cancer pathways: CYP3A4, PIK3R1, PIK3CD, ESR1, AKR1C3, EGFR, and CYP19A1." (PMID 39204124, 2024). "Among these, cytochrome P450 3A4 (CYP3A4) is a crucial enzyme responsible for converting paclitaxel into its active forms that exhibit anti-cancer properties." (PMID 38686048, 2024). "Understanding the mechanisms by which CDK9 and CYP3A4 contribute to cancer development and progression is essential for the development of new therapeutic strategies." (PMID 39498375, 2024). "Vinblastine is metabolized by CYP3A4, and this pathway is inhibited by other anticancer drugs currently co-administered with vinblastine in cancer chemotherapy (etoposide, adriamycin, lomustine, and teniposide)." (PMID 39682707, 2024). "Of particular note was the finding that to recover the observed data in cancer patients with moderate RI (CrCL 20 to 39 mL/min), reductions of hepatic CYP3A4 and CYP2C8 expression, which reflect the effects of RI, had to be included in the simulations." (PMID 37514108, 2023). "Based on the results of literature reports and network pharmacology analysis, this study aims to explore the anti-cancer effect and mechanism of quercetin-targeted inhibition of CYP3A4 on BC by inhibiting the metabolism of AA." (PMID 37710176, 2023). "A notable finding was that for recovery of the observed data in cancer patients with moderate RI (CrCL 20 to 39 mL/min), reductions of hepatic CYP3A4 and CYP2C8 abundances, which reflect the effects of RI, had to be included in the simulations." (PMID 37514108, 2023). "The Akt/Nrf2/CEBPB axis was mainly involved in the induction of CYP3A4 by cancer spheroid formation, and the inactivation of Akt through the inhibition of KCa1.1 induced the down-regulation of CYP3A4, which is involved in DOX metabolism." (PMID 37958656, 2023).